SERP2 (stress associated endoplasmic reticulum protein family member 2)
Description:
Interacts with target proteins during their translocation into the lumen of the endoplasmic reticulum. Protects unfolded target proteins against degradation during ER stress. May facilitate glycosylation of target proteins after termination of ER stress. May modulate the use of N-glycosylation sites on target proteins.
Synonyms: C13orf21; bA269C23.1
Tractability: Antibody: UniProt predicts a signal peptide or a membrane-spanning region. PROTAC: ubiquitination databases record sites on it.
Gene: Protein-coding gene on chromosome 13 (44,373,476 to 44,397,714, forward strand). Ensembl gene ENSG00000151778.
Subcellular location: Membrane; Endoplasmic reticulum membrane
Subcellular location (Human Protein Atlas): Endoplasmic reticulum
Gene Ontology:
Molecular function: protein binding
Biological process: endoplasmic reticulum unfolded protein response
Cellular component: endoplasmic reticulum; endoplasmic reticulum membrane; membrane
Genetic constraint (gnomAD): Loss-of-function variants: 2 observed, 2.34 expected, observed/expected ratio (o/e) 0.85, 90% interval 0.32 to 1.84. That is too few expected variants to judge how well the gene tolerates losing a copy. Missense variants: 28 observed, 30.53 expected, observed/expected ratio (o/e) 0.92, 90% interval 0.68 to 1.26. Synonymous variants: 20 observed, 11.91 expected, observed/expected ratio (o/e) 1.68, 90% interval 1.14 to 1.95.
Homologues: Orthologues: chimpanzee SERP2 (100% identical), dog SERP2 (100% identical), mouse Serp2 (100% identical), pig SERP2 (100% identical), rabbit SERP2 (100% identical), rat Serp2 (100% identical), zebrafish serp2 (100% identical), macaque SERP2 (83% identical), tropical clawed frog serp2 (80% identical), Drosophila melanogaster CG32276 (66% identical), Caenorhabditis elegans serp-1.1 (60% identical), Caenorhabditis elegans serp-1.2 (52% identical). Paralogues in human: SERP1 (91% identical).
Diseases named in the same sentence as SERP2 in open-access papers:
SERP2 is named in the same sentence as 10 diseases in open-access papers, as found by Europe PMC text mining. Sharing a sentence is not in itself a finding about the gene and the disease. The quoted sentences say what the papers report.
acute lymphoblastic leukemia (1 paper, 2023). Leukemia with an acute onset, characterized by the presence of lymphoblasts in the bone marrow and the peripheral blood. "In human cytogenetic studies, microdeletions of the SERP2 gene were reported to be associated with acute lymphoblastic leukemias in children with Down syndrome, and focal deletions of this gene were also identified in 2–6% of adult cases of acute lymphoblastic leukemia." (PMID 37176129, 2023).
arterial disease (1 paper, 2012). "For this reason, we have elected to assess plaque growth and responses to the viral anti-inflammatory serpin, Serp-2, in a range of models to determine whether the effects of this protein will be evident in different animal models of arterial disease." (PMID 23049756, 2012).
colorectal cancer (1 paper, 2020). A primary or metastatic malignant neoplasm that affects the colon or rectum. "The differentially methylated regions revealed the gene EPHB1, whose under‐expression leads to gastric carcinoma and invasion of colorectal cancer cells, and SERP2, which is positively correlated with body mass index (BMI) and abnormal glucose tolerance as well as colorectal cancer." (PMID 33392433, 2020).
glioma (1 paper, 2017). A benign or malignant brain and spinal cord tumor that arises from glial cells (astrocytes, oligodendrocytes, ependymal cells). "Major TGF-Beta-EMT inducing factors (RHOA, RAC1, ROCK2, CDC43 and LIMK1) and EMT transcription factors (TWIST1, SOX9, TRIM28 and SERP2) have among the highest risk scores in our glioma transcriptional model." (PMID 28916782, 2017).
leukemia (1 paper, 2021). A malignant (clonal) hematologic disorder, involving hematopoietic stem cells and characterized by the presence of primitive or atypical myeloid or lymphoid cells in the bone marrow and the blood. "Among them, PDE4D has been reported to act as a proliferation promoter in several different tumors, and mutations in SERP2 are associated with leukemia." (PMID 34565479, 2021).
tumor (2 papers, 2023 to 2025). "While direct studies in OC are more limited to SERP2 and NRK, their upregulation in this context suggests a possible role in inflammation-related signaling and tumor-stroma interaction, consistent with the inflammatory enrichment observed in our KEGG analysis." (PMID 40427104, 2025).
infection (1 paper, 2020). The state of being infected such as from the introduction of a foreign agent such as serum, vaccine, antigenic substance or organism. "In Myxomavirus infections, the deletion of Serp-1 or Serp-2 genes modifies this highly lethal infection in European rabbits (Oryctolagus cuniculus) to a benign local infection." (PMID 32244484, 2020).
vasculopathy (1 paper, 2020). "When Serp-2 is given to mice after implant of granzyme B-deficient aortic transplants, the efficacy for reducing graft vasculopathy is lost, indicating that Serp-2 immune-modulating functions in this transplant model are at least in part dependent upon blockade of granzyme B and apoptosis." (PMID 32244484, 2020).
SERP2 also shares sentences with these, for which no sentence is quoted: Down syndrome (1 paper); myxoma (1).